RBMXL1 (RBMX like 1)
Description:
RNA-binding protein which may be involved in pre-mRNA splicing.
Synonyms: KAT3; RBM1
Tractability: PROTAC: UniProt records ubiquitination sites on it; ubiquitination databases record sites on it; its protein half-life has been measured.
Gene: Protein-coding gene on chromosome 1 (88,979,456 to 88,992,960, reverse strand). Ensembl gene ENSG00000213516.
Subcellular location: Nucleus
Subcellular location (Human Protein Atlas): Nucleoplasm
Gene Ontology:
Molecular function: nucleic acid binding; RNA binding
Biological process: mRNA splicing, via spliceosome
Cellular component: spliceosomal complex; nucleus
Genetic constraint (gnomAD): Loss-of-function variants: 18 observed, 28.02 expected, observed/expected ratio (o/e) 0.64, 90% interval 0.44 to 0.95. The upper end of that interval is the gene's LOEUF score, 0.95, which puts it in group 4 of 6, group 1 being the genes least tolerant of losing a copy. Missense variants: 403 observed, 495.8 expected, observed/expected ratio (o/e) 0.81, 90% interval 0.75 to 0.88. Synonymous variants: 141 observed, 161.32 expected, observed/expected ratio (o/e) 0.87, 90% interval 0.76 to 1.
Homologues: Orthologues: macaque RBMXL1 (98% identical), pig RBMX (95% identical), mouse Rbmxl1 (94% identical), rat Rbmxl1 (93% identical), mouse Gm7324 (93% identical). Paralogues in human: RBMX (95% identical), RBMXL2 (69% identical), RBMY1B (59% identical), RBMY1F (59% identical), RBMY1J (59% identical), RBMY1A1 (59% identical), RBMY1D (59% identical), RBMY1E (58% identical), RBMXL3 (53% identical), CIRBP (28% identical), RBM3 (23% identical), MSI1 (23% identical), and 24 more.
Diseases named in the same sentence as RBMXL1 in open-access papers:
RBMXL1 is named in the same sentence as 7 diseases in open-access papers, as found by Europe PMC text mining. Sharing a sentence is not in itself a finding about the gene and the disease. The quoted sentences say what the papers report.
leukemia (3 papers, 2021 to 2024). A malignant (clonal) hematologic disorder, involving hematopoietic stem cells and characterized by the presence of primitive or atypical myeloid or lymphoid cells in the bone marrow and the blood. "RC43T:LNCaP compared with RC43N:HPr1AR cells revealed basal and 1α,25(OH)2D3-regulated switches in CoA and CoR; for example, CoA gains included RBMXL1, a transcriptional regulator identified in leukemia, alongside two other RBM family members." (PMID 37082578, 2023). "CBX5 was reported to had higher expression in high than in low c-Kit leukemia stem cell populations, and elevated CBX5 expression was associated with increased expression of RBMX and RBMXL1, which maintain the chromatin state essential for the survival of acute myeloid leukemia cells." (PMID 38798352, 2024). "RBMX and RBMXL1 could contribute to leukemia develop_x005fment and maintenance." (PMID 34804951, 2021).
melanoma (2 papers, 2013 to 2017). A malignant, usually aggressive tumor composed of atypical, neoplastic melanocytes. "MUC19, PAICS, RBMXL1, KIF23 have been identified in melanoma, which might deserve further investigations the role in cancer." (PMID 28159935, 2017). "We also identified mutations in four genes (MUC19, PAICS, RBMXL1, KIF23) never reported in melanoma, which might deserve further investigations." (PMID 23704925, 2013).
breast carcinoma (1 paper, 2020). "RBMXL1 (RNA binding motif protein) encodes a splicing protein that suppresses tumor proliferation, and promotes apoptosis in gastric and breast cancer." (PMID 32581649, 2020).
RBMXL1 also shares sentences with these, for which no sentence is quoted: acute myeloid leukemia (1 paper); cancer (1); infection (1); tumor (1).